CD244 (CD244 molecule)
Diseases named in the same sentence as CD244 in open-access papers (continued):
Sharing a sentence is not in itself a finding about the gene and the disease.
cancer (49 papers, 2013 to 2025). A tumor composed of atypical neoplastic, often pleomorphic cells that invade other tissues. "Accumulating research has linked PD-1 and CD244 inhibitory signaling to the maintenance of an exhausted phenotype in NK cells and T cells in chronic infection and cancer." (PMID 33154753, 2020). "Therefore, we intended to further explore the genetic mutations or alteration of CD244 in various cancers to outline its roles in human tumors." (PMID 38633624, 2024). "Hence, we further explored the genetic alterations of CD244 to study its mutations and roles in cancers." (PMID 38633624, 2024). "After early studies established that CD244 expression on these cell types is altered under specific pathologic conditions, more recent research has linked CD244 inhibitory signaling to the maintenance of an exhausted phenotype in NK cells and T cells in chronic infection and cancer." (PMID 30546369, 2018). "SELENOP and CD244 were highly expressed in the adjacent cancer tissues, while PKMYT1 and LAG3 were highly expressed in the cancer tissues." (PMID 40821907, 2025). "We found significant differences in the expression of SELENOP, PKMYT1, LAG3 and CD244 between the cancer tissues and adjacent cancer tissues." (PMID 40821907, 2025). "We exploited it to certify the relevance of CD244 expression in 14 functional states in the single cell of distinct cancers." (PMID 38633624, 2024). "Together, these data suggest that CD244 functions as a novel immune checkpoint receptor that restricts function and differentiation of monocytes/macrophages in cancer patients." (PMID 38424542, 2024). "We also discovered a correlation between genetic alterations of CD244 and clinical prognosis in several cancers." (PMID 38633624, 2024). "The maximum alteration frequency of CD244 in cancers was above 15%, in which "amplification" is the primary type of genetic alteration, followed by "mutation"." (PMID 38633624, 2024). "Previous studies have demonstrated that CD244 acts as a cell surface receptor in immune response and regulation, and is involved in a series of biological processes in the pathogensis of cancer." (PMID 38633624, 2024). "Altogether, CD244 plays an inhibitory (or protective) role in the inition and progression of cancer." (PMID 38633624, 2024). "Our study offers a comprehensive overview of CD244 in human tumors, revealing CD244 as a potential prognostic biomarker and immunotherapeutic target in cancers." (PMID 38633624, 2024). "In our present study, we conducted a comprehensive pan-cancer analysis on the roles of CD244 expression." (PMID 38633624, 2024). "Next, we used BEST database to explore the relationship between CD244 expression and immunotherapy response in cancer patients." (PMID 38633624, 2024). "Previous studies have shown that CD244 is related to many immune-related diseases, involving cancers and infectious diseases, and is involved in their onset and progression [5,]." (PMID 38633624, 2024). "Other important genes in this list downregulated by TOX2-shRNA, such as ITGB7, SLAMF1, CD244, DPYSL3, KRT80 and KRT7, have been implicated in cancer progression or drug resistance." (PMID 37032358, 2023). "We found that PTPN6 expression was positively correlated with PDCD1, CD274, CTLA4, LAG3, HAVCR2, and CD244 in most cancer types in TCGA, including LGG and GBM." (PMID 37737713, 2023). "In many different cancer types, CD244 is viewed as an anti-inflammatory and pro-tumor receptor, with CD244 inhibition suggested as a possible therapy to overcome checkpoint inhibitor resistance." (PMID 36945037, 2023). "One noteworthy SLAM family member, CD244, holds paramount importance across various diseases, especially cancers." (PMID 37835502, 2023).
cancer (continued). "Strikingly, ACACA expression exhibited significant negative correlations with the immune checkpoint-related genes (PDCD1, LAG3, LAGLS9, IDO1, CD244, CTLA4 and TIGIT), while showing positive associations with other genes (TGFBR1, KDR, IL10RB, CD160 and CD274) across most cancer types." (PMID 41169354, 2025). "Interestingly, our findings demonstrated a relationship between the CD244 genetic alterations and the survival rate of cancer patients with BRCA, COAD, and PCPG." (PMID 38633624, 2024). "These investigations could provide valuable insights into the therapeutic potential of targeting CD244 on monocyte-lineage cells for treating a wide range of human cancers." (PMID 38424542, 2024). "Furthermore, CD244 expression in monocyte-lineage cells acts as a predictive marker in cancer patients." (PMID 38424542, 2024). "Moreover, we investigated the relations between the expression level of CD244 and the survival rate of patients with cancer." (PMID 38633624, 2024). "Furthermore, CD244 expression in monocyte-lineage cells serve as a prognostic marker in cancer patients." (PMID 38424542, 2024). "In addition, CD96, CD244 have been identified as new checkpoint receptor targets for cancer immunotherapy, and TGFβ1 has been found to play a key role in the EMT process in ccRCC." (PMID 37679715, 2023). "Research indicated that CD244 had opposing regulatory effects on NK cells in different cancers." (PMID 33841431, 2021). "FoxO could inhibit T cell effector function through inhibition of T-bet expression; CD244 could be indicative of an exhausted phenotype and is related to cancer immune tolerance; and finally TGFBR1 is the main receptor for the immunosuppressive cytokine TGFβ." (PMID 33076479, 2020). "In human cancers, CD244 also shows increased expression on exhausted CD8+ T cells." (PMID 30546369, 2018). "Inhibitory CD244 signaling in NK cells has also been demonstrated in human cancer patients." (PMID 30546369, 2018). "In mouse models of cancer, CD244 is expressed on CD8+ T cells with an exhausted phenotype." (PMID 30546369, 2018). "However, the function of CD244 in pan-cancer has not been fully understood." (PMID 38633624, 2024). "The activation status of the different populations was subsequently analyzed by monitoring the expression of CD244, DNAM-1 and 4-1BB, three NK cell activating receptors identified as good targets for cancer immunotherapies." (PMID 41041306, 2025). "CD244 is increasingly expressed on exhausted CD8+ T cells with decreased production of IL-2 and IFN-γ in both mouse and human cancers." (PMID 38633624, 2024). "There are many activating receptors expressed by NK cells, and some examples of relevance to cancer immunotherapy include NKp46, NKp30, DNAM-1 (CD226), 2B4 (CD244), activating KIR, NKG2D, NKG2C, and NKp44." (PMID 38223411, 2024). "Here, our results revealed a positive correlation between the expression of CD244 and the immune infiltrations of CD8+ T cells, B cells, dendritic cells, and monocytes in many cancer types, especially like UCEC." (PMID 38633624, 2024). "Prior research has indicated a connection between elevated CD244 levels in CD8+ T cells and increased PD-1 expression, suggesting CD244’s role in the exhaustion of these T cells in chronic viral infections and cancer." (PMID 37835502, 2023). "A vaccine targeting CD244, leveraging antibodies against CD244 or its natural ligand CD48, has been developed to enhance T-cell activation, offering a novel approach against infectious diseases and cancers." (PMID 39092217, 2024). "In previous studies, CD244 has already been shown to be co-expressed on CD8+ T-cells with other immunoregulatory receptors, including PD-1, CD160, CTLA-4, and TIM-3 in both mouse cancer models and patients with cancer." (PMID 34944879, 2021).
cancer (continued). "Corresponding to inhibitory signaling in NK cells, CD244 demonstrates an inhibitory function when expressed at higher concentrations on CD8+ T cells that demonstrate an exhausted phenotype in chronic viral infection and cancer." (PMID 30546369, 2018). "For example, blocking CD244 signaling on exhausted CD8+ T-cells may ameliorate the exhausted phenotype and contribute to re-activation of memory CD8+ T cells in cancer." (PMID 30546369, 2018). "However, a comprehensive pan-cancer analysis regarding the roles of CD244 across other cancer types is not yet clear." (PMID 38633624, 2024).
infection (28 papers, 2010 to 2026). The state of being infected such as from the introduction of a foreign agent such as serum, vaccine, antigenic substance or organism. "We first sought to explore whether infection of macrophages with MCMV resulted in a reduced recognition by CD244 due to the loss of CD48 on the cell surface." (PMID 24626474, 2014). "We additionally noted a trend towards association with infection for stem cell-like memory T cells expressing markers of exhaustion (CD39 and CD244) and senescence (CD57)." (PMID 40475763, 2025). "Infection was associated with the upregulation of proinflammatory genes CXCL10, IFNG, and IL15, alongside several NK and T cell activation markers such as CD244, CD40LG, and CD226." (PMID 39774119, 2025). "Since only one report analyses CD244 function and shows an upregulation in the chronic human CD, we wanted to elucidate if CD244 represents a potential regulatory pathway in the acute stage of infection." (PMID 35812458, 2022). "Furthermore, SphK2-deficient neutrophils expressed lower levels of the immunosuppressive marker CD244 during infection." (PMID 41660628, 2026). "As the expression of immune checkpoint molecules on the DC may contribute to tolerogenic DCs inhibitory properties, we analyzed PD-1, TIGIT, LAG3, and CD244 expressions in cDCs and pDCs in the livers of mice at 24 weeks after infection." (PMID 38787028, 2024). "Notably, analysis of cytokine/chemokine expression (Olink) identified a significant increase of activators of cytotoxic NK cells, including IL-12B and the immunoregulatory signaling molecule CD244, in less severe infection." (PMID 37327781, 2023). "There were expression differences in Cd244, but not Itln1 or Ly9, over the course of infection between resistant C57BL/6 and susceptible A/J and BALB/c." (PMID 21085469, 2010). "After primary infection, the EBV virus persists lurking dormant inside B cells and EBV infected B cells are particularly sensitive to CD244-mediated NK cell lysis." (PMID 32204481, 2020). "We hypothesize that CD48 participates in cell activation in response to infection and inflammation via interactions between CD48 and CD244 on mast cells, eosinophils, T-cells, and basophils." (PMID 30306094, 2018). "The cell surface glycoprotein 2B4 (CD244) is related to CD2 and is implicated in the regulation of NK- and T-cell function and it was expressed on D21, but not earlier during infection." (PMID 21249199, 2011). "Namely, CD5, CD8A, CD6 and CD244, C-C and C-X-C motif chemokines (CXCL5 CXCL6, MCP-4, and CCL20), as well as CD40, PDL-1, CUB domain-containing protein 1 (CDCP1) and interleukin-12B (IL-12B) were elevated in the late infection group compared to the unexposed group." (PMID 41510260, 2025). "Results from this study also revealed that CD244 or its ligand CD48 blockade may recover T-cell proliferation, cytokine production and cytotoxicity of exhausted HBV-specific CD8+ T cells in chronic infection but not in acute and resolved infection." (PMID 25789969, 2015).
infectious disease (3 papers, 2013 to 2024). A disorder directly resulting from the presence and activity of a microbial, viral, or parasitic agent in humans. "The role of CD244/2B4 on CD8 T cells in infectious diseases has been reported recently." (PMID 23638187, 2013).
immune disorders (2 papers, 2022 to 2023). "In summary, our study demonstrated that CD244 instead of CD160 is an important immune regulator involved in the process of T cell aging, making it an effective therapeutic target to improve age-related immune disorders and comorbidities." (PMID 35386693, 2022).
metabolic disease (2 papers, 2022 to 2024). A congenital disorder (due to inherited enzyme abnormality) or acquired (due to failure of a metabolically important organ) disorder resulting from an abnormal metabolic process. "CD244+CD160- CD8+ T cells displayed the increased activity of β-GAL, higher production of cytokines, and severe metabolic disorders, which were characteristics of immune aging." (PMID 35386693, 2022). "Moreover, only CD244+CD160- CD8+ T cells were identified as senescent population, manifested by increased activity of β-GAL, higher production of cytokines, and severe metabolic disorders." (PMID 35386693, 2022).
respiratory disease (1 paper, 2024). "The search for CD244-targeted therapies opens new vistas for the treatment of COPD, providing innovative strategies to address this debilitating respiratory disease." (PMID 39423200, 2024).
CD244 also shares sentences with these, for which no sentence is quoted: colitis (4 papers); multiple myeloma (4); Hepatitis B (3); influenza (3); non-small cell lung carcinoma (3); rheumatoid arthritis (3); chronic GVHD (2); chronic viral hepatitis (2); gastric cancer (2); hematopoietic cancers (2); immuno-deficiency (2); lymphoma (2); myelodysplastic syndrome (2); pancreatic cancer (2); triple-negative breast carcinoma (2); adult T cell lymphoma (1); Anxiety (1); astrocytoma (1); atherosclerosis (1); autoimmune hepatitis (1); bacterial infection (1); bladder cancer (1); breast tumors (1); cervical cancer (1); Chagas disease (1); chronic hepatitis (1); chronic hepatitis B (1); colon adenocarcinoma (1); Crohn disease (1); cutaneous leishmaniasis (1).
A further 25 diseases each share a sentence with CD244 in 1 paper.